CRP (C-reactive protein)
Diseases named in the same sentence as CRP in open-access papers (continued):
Sharing a sentence is not in itself a finding about the gene and the disease.
Sepsis (continued). "This study showed that PCT levels are of value in differentiating between sepsis and SIRS in critically ill patients and more helpful than CRP, IL-6, or LBP levels." (PMID 21687569, 2011). "Serum sTREM-1 levels reflected the severity of sepsis more accurately than those of CRP and PCT and were more sensitive for dynamic evaluations of sepsis prognosis." (PMID 21356122, 2011). "Similar findings were reported for LBP (AUC = .53) and CRP (AUC = .56) plasma concentrations on ICU admission in a heterogeneous population of postoperative patients with SIRS, sepsis or septic shock." (PMID 21901123, 2011). "Yucel and co-workers did a prospective study of 40 patients with severe sepsis and mechanical ventilation, and assessed serum levels of ANP, BNP, cTnI and C-reactive protein (CRP) at ICU admission, and two days later of ICU discharge." (PMID 22758615, 2011). "This single-centre prospective observational study showed that serum PCT levels are more valuable than serum CRP, LBP, and IL-6 levels in discriminating sepsis from SIRS in critically ill patients." (PMID 21687569, 2011). "The purpose of this study was to track changes in serum sTREM-1, CRP and PCT levels in patients with sepsis and to compare the predictive values of these three factors for assessing sepsis and establishing prognosis." (PMID 21356122, 2011). "Using NGAL as the dependent variable, the presence of sepsis, the renal variables from the SOFA score, CRP, and serum cystatin C were independently related to NGAL levels at initiation of RRT." (PMID 20122150, 2010). "In contrast, another study regarded PCT as superior to CRP measurement and concluded that PCT should be used to diagnose sepsis in ICUs." (PMID 21078153, 2010). "All variables found to be statistically significant at a 10% level in the univariate analysis (sepsis, APACHE II score, SOFA score, CRP, and NGAL) were subjected to multivariate Cox regression analysis." (PMID 20122150, 2010). "The non-sepsis group had mean CRP concentrations of 8.5 (CI 6–11) mg/L at admittance to the NICU, and 9.1 (CI 6.4–11.8) mg/L as highest CRP during treatment." (PMID 19152691, 2009). "Infection rate (as defined by leucocytosis, temperature >38°C and C-reactive protein >8 mg/l) on ICU was 18%, main complications were bronchopulmonary (n = 18), sternal infection (n = 3) and sepsis (n = 2)." (PMID 19772645, 2009). "Among several markers of inflammation and sepsis, PCT and C-reactive protein (CRP) markers are being studied to investigate their accuracy for the diagnosis of bacterial infections." (PMID 19578505, 2008). "• CRP levels decrease less rapidly in children with more severe septic conditions (septic shock, MODS) in contrast to those with sepsis/severe sepsis." (PMID 17598889, 2007). "sTREM-1 has been found to be more sensitive and specific than both CRP and PCT in diagnosing sepsis in ICU patients with SIRS." (PMID 17362525, 2007). "Nevertheless, similarly to the results of Yentis and colleagues in patients with sepsis, in our VAP patients the decrease of CRP levels was significantly predictive of survival, with OR = 7.40." (PMID 16956405, 2006). "The diagnosis of sepsis post transplant may be difficult, because immunosuppressive agents influence parameters, which are indicative for inflammation such as the levels of C-reactive protein (CRP) and the white blood count (WBC) and moreover, these parameters can be elevated during graft rejection." (PMID 16895603, 2006). "Diagnostic reliability of serum PCT was not compared with CRP or other infection markers, such as leukocyte count, given that these laboratory tests were not standardized and were performed according to techniques of each participating hospital, and they were used to define sepsis." (PMID 16709255, 2006). "Overall, both CRP and PCT are useful for initial assessment and follow-up in suspected sepsis." (PMID 41597433, 2026).
Sepsis (continued). "In children with sepsis or other infectious conditions, CRP is more likely to be higher in females than males, however, evidence is lacking on sex differences in CRP in the neonatal population." (PMID 41689155, 2026). "SeptiCyte® RAPID was significantly better for sepsis diagnosis than CRP [0.75 (CI95% 0.70-0.80)] (p =0.003) but without significant differences with PCT [0.80 (CI95% 0.75-0.84)]." (PMID 41729344, 2026). "Although Gal-9, sTREM-1, and sCD25 demonstrated statistically significant clinical value in patients with sepsis, their AUC values were not higher than those of established biomarkers such as CRP and lactate." (PMID 41225969, 2025). "This study aimed to evaluate the Endothelial Activation Stress Index (EASIX) and its modified version (m-EASIX, which replaces creatinine with C-reactive protein [CRP] (mg/dL)) as early predictors of severe CRS and ICANS, as well as tools to distinguish CRS from sepsis." (PMID 41573561, 2025). "Infections may result in either leukocytosis or leukopenia; however, inflammation markers like CRP (C-reactive protein) or ESR (erythrocyte sedimentation rate) are usually elevated, and blood cultures may be positive in cases of bacteremia or septicemia." (PMID 40656200, 2025). "Although laboratory-based sepsis markers such as elevated CRP, leukopenia, and hypoalbuminemia were explored, none showed statistically significant associations with mortality in our cohort." (PMID 41153495, 2025). "The ability of CRP to effectively rule out bacterial infection and sepsis makes it a potentially useful biomarker in the initial assessment of patients with a suspected infection, unfortunately only at very low levels." (PMID 40598497, 2025). "CRP and PCT are commonly used biomarkers in sepsis diagnosis, but their specificity can be limited in patients with underlying conditions such as cancer, where elevated levels may result from non-infectious causes." (PMID 41303127, 2025). "Another constraint is the lack of data on PCT and CRP, pivotal sepsis biomarkers, because these markers weren’t routinely tested in our ER." (PMID 41432366, 2025). "CRP kinetics was not proved to have any correlation with sepsis development, in addition to cfDNA and NET kinetics." (PMID 40731775, 2025). "In this case, empirical antibiotics were started for presumed sepsis after investigations revealed raised C-reactive protein (CRP) and mild hypokalemia with no clear infectious focus." (PMID 41555989, 2025). "This excessive inflammatory response, commonly referred to as Cytokine Storm Syndrome (CSS) or CRS, manifests as high fever, elevated CRP and ferritin levels, and cytopenias that can lead to lung damage, ARDS, Multiple Organ Dysfunction Syndrome (MODS), sepsis, and ultimately death." (PMID 40187234, 2025). "On the other hand, few infants with a sepsis diagnosis and none with culture-proven sepsis had a CRP above 30 mg/L at 1 or 12 h." (PMID 41441318, 2025). "The main objective of this study was to determine kinetics of plasma PCT (pPCT) and CRP in dogs with sepsis, non-infectious systemic inflammatory response syndrome (nSIRS) and healthy dogs." (PMID 40607352, 2025). "Currently, CRP and PCT are the most widely researched and utilized biomarkers in sepsis." (PMID 40568710, 2025). "In addition to clinical scores, biomarkers, such as procalcitonin (PCT) and C-reactive protein (CRP), are frequently used to support sepsis diagnosis and monitor disease progression." (PMID 40804855, 2025). "However, significant differences were found between the groups in twins, history of asphyxia, presence of preoperative sepsis, gestational age, postoperative SBS, and preoperative CRP level (P = 0.013, P = 0.002, P = 0.003, P = 0.005, P < 0.001, P = 0.042)." (PMID 41409265, 2025).
Sepsis (continued). "Procalcitonin, C-reactive protein (CRP), CD14, and interleukin-6 can qualify as general sepsis biomarkers by broad applicability across all sepsis subtypes, consistently reported across adult, pediatric, and neonatal cohorts, reflecting a conserved pathophysiological role." (PMID 40478618, 2025). "CRP levels were drastically elevated in the sepsis group (60.1 mg/L, IQR: 32.3–103.9) compared with the non-sepsis group (4.1 mg/L, IQR: 1.9–9.8; p < 0.001), suggesting substantial systemic inflammation." (PMID 40863575, 2025). "However, the highly elevated CRP, WCC, and cardiac troponins during sepsis indicated that both significant inflammatory response and myocardial injury took place." (PMID 40310393, 2025). "Among infants without sepsis, CRP was higher at all time points in infants who did vs. those who did not receive antibiotics (p < 0.001)." (PMID 41441318, 2025). "Although median CRP was low among term infants without sepsis born after PROM, we found CRP values above 60, 80, and 90 mg/L at 1, 12, and 36 h, respectively." (PMID 41441318, 2025). "CRP was significantly higher among non-survivors with sepsis both with microbiology and non-microbiology proof of infection." (PMID 40685448, 2025). "Patients with sepsis and liver cirrhosis have lower LBP and CRP levels compared to sepsis patients without liver cirrhosis." (PMID 39997462, 2025). "The daily CRP protocol did not reduce the use of antibiotics for sepsis patients and was inconclusive for safety." (PMID 41316366, 2025). "Similarly to the previous study, our results showed that WRS levels positively correlated with the SOFA score and creatinine, P-SEP, CRP, PCT, and lactate levels in patients with sepsis." (PMID 41153306, 2025). "Infection was excluded after having negative pan-cultures, especially as there were no clinical or laboratory signs of septicemia except for a mildly elevated C-reactive protein level of 9 mg/L." (PMID 40846356, 2025). "Conversely, high dose intravenous vitamin C did not affect CRP levels in sepsis with severe acute respiratory failure." (PMID 40091112, 2025). "In contrast, median CRP was above the reference range (<10.5 mg/L) in dogs with nSIRS (100.7 mg/L; IQR 67–141.9) or sepsis (131.9 mg/L; IQR 75.7–194.8) and significantly decreased within the first 4 days of successful antimicrobial treatment of sepsis." (PMID 40607352, 2025). "In severe sepsis, patients with DIC exhibited elevated levels of PCT and CRP." (PMID 41321462, 2025). "Severe anemia, thrombocytopenia, leukopenia, leukocytosis, hyperbilirubinemia, CRP, and procalcitonin levels at admission were not statistically significant in predicting mortality in cases of severe sepsis or septic shock." (PMID 40115724, 2025). "Both CRP and PTX3 levels increase during infection, particularly bacterial infections, and may be useful in predicting sepsis." (PMID 40722110, 2025). "While the predictive capacity of PCT aligns with our study's findings, we did not identify CRP as an independent predictor of sepsis, potentially attributed to the limited case numbers in their investigation." (PMID 40933706, 2025). "In this study, the AUC value of presepsin in predicting mortality in patients with sepsis was found to be 0.819, and it was reported that there was no statistical difference between the procalcitonin and CRP levels of survivors and non-survivors." (PMID 40172393, 2025). "In addition, several biomarkers, including C-reactive protein (CRP), procalcitonin, and white blood cell (WBC) count, are used in sepsis diagnosis." (PMID 40917940, 2025). "In patients with sepsis complicated with ARDS, sivelestat sodium treatment significantly improved the inflammatory indicators (IL-6, PCT, CRP) and the oxygenation index (PaO2/FiO2), and significantly reduced the duration of mechanical ventilation time and ICU stay, and the incidence of VAP." (PMID 40842872, 2025).
Sepsis (continued). "Studies with patients who did not undergo CRP or PCT testing to support neonatal sepsis diagnosis were also excluded." (PMID 40970024, 2025). "Notably, TFEs have beenemployed to develop biosensors for C-reactive protein (CRP), a keybiomarker of sepsis." (PMID 41244407, 2025). "Although many studies regard PCT as superior to CRP, it is not a definitive test for diagnosing sepsis, as elevated PCT levels can also occur in other conditions." (PMID 41011807, 2025). "Research is needed on the long-term outcomes of infants with inflammation, as evidenced by an elevated CRP, but not sepsis, after PROM." (PMID 41441318, 2025). "Among infants who were not diagnosed with sepsis, the median CRP at 36 h was 29 mg/L in those receiving antibiotics and 0 mg/L in those who did not receive antibiotics (p < 0.001)." (PMID 41441318, 2025). "Laboratory Investigations showed leukocytosis, AG acidosis, decreased renal functions, elevated liver enzymes, elevated NT-ProBNP suggestive of right heart failure, elevated CRP suggestive of inflammatory response and positive blood culture for MSSA consistent with sepsis." (PMID 41523545, 2025). "Of severe infection episodes for which sepsis work-up tests were done, the proportion of test results meeting their respective thresholds for clinical concern ranged from 4.8% for elevated ALT to 24% for elevated CRP." (PMID 40661255, 2025). "The levels of white blood cell, blood glucose, and C-reactive protein in the case with cutaneous myiasis were more stable than the other case without cutaneous myiasis but with sepsis shock." (PMID 40395508, 2025). "Additionally, the CRP (p = 0.022), SOFA score (p = 0.000), and APACHE II score (p = 0.003) were significantly elevated in sepsis patients with ARDS." (PMID 40396530, 2025). "In this study, we aimed to retrospectively examine CRP as a marker of inflammation in term infants born after PROM but not diagnosed with sepsis and to assess the correlation between CRP and different background variables and clinical characteristics." (PMID 41441318, 2025). "In this study, serum levels of IGFBP-3, C-reactive protein, procalcitonin, lactate, interleukin-6, and mid-regional pro-adrenomedullin were measured upon admission to the internal medicine unit (IMU) in 139 patients with microbiologically confirmed sepsis." (PMID 40724799, 2025). "Electrochemical biosensors are highly relevant for sepsis detection, as they translate biological recognition events, such as the binding of biomarkers, e.g., PCT or CRP, into measurable electrochemical signals, which relate to the target molecule concentration levels at the transducer surface." (PMID 40710052, 2025). "CRP therefore is not a useful marker to discriminate between sepsis and nSIRS, but reflects systemic inflammation in dogs, which is in agreement with a previous study." (PMID 40607352, 2025). "Among the excluded studies, the most common reasons were studies evaluating infections other than sepsis and those focused only on absolute CRP level without assessing diagnosis accuracy." (PMID 41429071, 2025). "Secondary objectives include a head-to-head comparison with established biomarkers sepsis biomarkers (PCT, CRP, lactate) and clinical scoring systems (qSOFA, NEWS2, SOFA), as well as decision curve analysis to evaluate net clinical benefit and an economic evaluation of model implementation." (PMID 41488103, 2025). "Our study demonstrates that plasma sLOX-1 levels in SIRS/sepsis are independent of traditional inflammatory markers like CRP and procalcitonin, contrasting with preclinical evidence suggesting a role for inflammation in LOX-1 shedding." (PMID 39948564, 2025). "Significant progress has been made in biosensor technology in recent years to identify sepsis biomarkers, such as procalcitonin (PCT), C-reactive protein (CRP), and interleukins (ILs), each of which provides important information on inflammation and early immunological responses." (PMID 40710052, 2025).
Sepsis (continued). "Comparable trends were observed for CRP levels, which showed a significant increase only in the sepsis cohort on day 2, compared to the pneumonia and no complication cohorts." (PMID 40367515, 2025). "Furthermore, several studies incorporated within the present meta-analysis assessed the collective predictive capacity of miRNAs, IL-6, PCT, CRP, SOFA score, and additional markers for sepsis mortality." (PMID 40135054, 2025). "They found significantly higher salivary CRP levels in neonates with sepsis compared to those without." (PMID 40871545, 2025). "This study aimed to investigate the clinical characteristics of children with sepsis and septic shock, with emphasis to evaluate the predictive value of C-reactive protein (CRP), procalcitonin (PCT), and nucleated red blood cell (NRBC) count in pediatric sepsis and septic shock patients." (PMID 40895306, 2025). "We assume that PCT in combination with clinical scores was outperformed by serum HNL and CRP + leucocyte count because the combinations integrated different aspects of sepsis without significantly overlapping in information." (PMID 40598497, 2025). "The present findings indicate that the measurement of CVP, SOFA score, CRP levels, lactate levels, and RRI reduction after 24 h of ICU treatment can serve as valuable predictive indicators for the early detection of SA-AKI in sepsis patients." (PMID 39864312, 2025). "Standard inflammatory markers such as leukocyte count, PCT, and CRP, were elevated in both groups without significant distinction-indicating that these are rather not suitable to differ the sepsis subtypes." (PMID 40510342, 2025). "In healthy infants and infants with sepsis, CRP rose gradually from ages 1 h to 12 h to 36 h, while in infants without sepsis treated with antibiotics, CRP rose from 1 h to 12 h and then gradually decreased towards 36 h." (PMID 41441318, 2025). "CRP, PCT, D-dimer, and ferritin can reflect the severity of sepsis." (PMID 39891057, 2025). "For infections without septicemia, encapsulated foci warrant surgical debridement if persistent after 48 h of appropriate antibiotics (e.g., <50% CRP decline)." (PMID 41001381, 2025). "Additionally, elevated CRP, FPG, and HbA1c levels postoperatively were strong predictors of sepsis, reinforcing the role of systemic inflammation and poor glycemic control in infection susceptibility." (PMID 40761819, 2025). "Available conventional sepsis screening markers, including hematologic indices and CRP, were not reliable early markers for EONS." (PMID 40171168, 2025). "Studies have demonstrated that C-reactive protein, procalcitonin, tumor necrosis factor α, interleukin-6, and neutrophil surface receptors (CD64) are currently widely utilized as biomarkers for monitoring sepsis." (PMID 40867545, 2025). "Norwegian consensus guidelines define culture-negative sepsis as CRP > 30 mg/L combined with clinical signs of systemic infection and antibiotic treatment for ≥5 days." (PMID 41441318, 2025). "Therefore, performing LPs based solely on serum CRP values of different cut-offs remains questionable, especially when evaluating EOS compared to late-onset sepsis." (PMID 41009903, 2025). "The areas under the curve (AUCs) of the receiver operating characteristic (ROC) curves of CRP, PCT and the NRBC count for the prediction of sepsis in children were 0.746 [95% confidence interval (CI) 0.650–0.842], 0.868 [95% CI 0.818–0.912] and 0.923 [95% CI 0.857–0.944], respectively." (PMID 40895306, 2025). "The diagnosis of sepsis was made on average 12.5 ± 9.4 days after surgery and CRP levels at baseline, at 24h and 48h after surgery did not correlate with its onset." (PMID 38834580, 2024). "Key parameters for assessing and predicting sepsis in NICUs patients include low birth weight, prematurity, perinatal history, premature rupture of membranes (PROM), C-reactive protein (CRP), white blood cell count (WBC), platelet count (PLT), heart rate, and respiratory rate and function." (PMID 39408019, 2024).